CKS2 (CDC28 protein kinase regulatory subunit 2)
Diseases named in the same sentence as CKS2 in open-access papers (continued):
Sharing a sentence is not in itself a finding about the gene and the disease.
tumor (continued). "This decrease in tumor weight is primarily due to Bay’s effects on inhibiting the expression of genes regulating the cell cycle and cell proliferation, including CCND1, E2F1, CKS2, and Ki67." (PMID 38994944, 2024). "In addition, the results show that CKS2, PCNA, CHEK1, and NCAPG2 are also involved in the regulation of tumor DNA replication and mismatch repair." (PMID 38937855, 2024). "CKS2 overexpression is correlated with aggressive tumor development in CRC, meaning that CKS2 might function as a decent CRC biomarker." (PMID 36900162, 2023). "Two of these, CKS2 and RIMS3, were shown to be substantially expressed in tumor tissues." (PMID 36733434, 2023). "By comparison between IHC of CKS2 expression in 80 OS and 41 non-tumor tissues, it was found that the expression of CKS2 in OS tissues was significantly higher than that in non-tumor tissues (P < 0.005)." (PMID 35410253, 2022). "Firstly, we used the data from the TCGA database to examine CKS2 gene mutation and copy number variation (CNV) and found that CKS2 gene mutation and CNV were not significantly different between normal lung and tumor tissues." (PMID 36010686, 2022). "Results revealed both the CKS2 and RMI2 are higher expressed in tumor than normal lung tissues." (PMID 33083148, 2020). "When compared to saline controls, methotrexate significantly inhibited the growth of control tumors with low CKS protein levels (**p = 0.0014), but did not affect Cks2-overexpressing tumor growth (p = 0.37)." (PMID 29383129, 2017). "Statistical analysis of paired tumor and normal adjacent samples as well as of non-paired samples using the Wilcoxon rank-sum and Wilcoxon singed-rank tests, respectively, showed that CKS2 expression was significantly higher in cancer tissues than in normal tissues (P < 0.001)." (PMID 34729099, 2021). "Heat shock-activated HSF1 is mainly responsive to the expression of heat shock proteins, while activation of HSF1 in tumor tissues is predominantly responsible for controlling the expression of non-heat shock proteins, e.g. CKS2, LY6K, RBM23, CCT6A, CKS1B, ST13 and EIF4A2." (PMID 25199534, 2014). "Although the level of CKS2 expression was significantly higher in the tumor tissue than in the adjacent non-cancer and normal colorectal tissues, there were certain discrepancies in the correlation between CKS overexpression at the mRNA and protein levels and lymph node metastasis." (PMID 24137409, 2013). "In addition, CKS2 overexpression was correlated with aggressive tumor progression in CRC, which indicated that CKS2 may serve as a good CRC biomarker." (PMID 24137409, 2013). "While the initiating cells in recurrent tumors were mainly related to the cell cycle such as MKI67, CKS2, ANLN, CDC20, CDCA8, CENPF, inflammatory signals no longer drive anti-tumor immunity." (PMID 41601649, 2026). "In contrast, Ktrans maps of CKS tumors do not exhibit the center/ rim pattern regardless of tumor size (CKS-1 vs. CKS-2)." (PMID 36011011, 2022). "Analysis of tumor and non-tumor tissues from our cohort of 102 patients with PDAC showed that CKS2 mRNA levels were higher in tumor tissues." (PMID 29764514, 2018).
cancer (43 papers, 2013 to 2025). A tumor composed of atypical neoplastic, often pleomorphic cells that invade other tissues. "CKS2 is expressed in a variety of tissues in the human body, but its abnormal expression is associated with cancer in a variety of systems." (PMID 39188686, 2024). "These unique functions based on CKS2 make it frequently associated with pathological changes in cancer." (PMID 39188686, 2024). "At the same time, abnormal CKS2 expression is often associated with poor clinical outcomes and thus can be used as a potential predictor of survival in cancer patients." (PMID 39188686, 2024). "It clearly showed that amplification is the most common alteration observed in BOP1, PLAU, SERPINE1, and CKS2 across the cancers, whereas in CCNA2, mutation and deep deletion are prevalent." (PMID 36203433, 2022). "Mechanistically, transcription factor E2F1 enhanced CKS2 expression through binding to its promoter and CKS2 regulated the cancer-associated PI3K–AKT pathway." (PMID 36096885, 2022). "Our analysis of TCGA data confirmed this, suggesting that CKS2 can be a diagnostic marker for a variety of cancers." (PMID 35663965, 2022). "From qPCR screening, we identified and validated that the cancer gene CKS2 encoding Cyclin-dependent kinases regulatory subunit 2 is the most upregulated cell cycle regulator when OTUD6A is overexpressed." (PMID 33669244, 2021). "Overexpression of CKS2 is determined in several cancer types and indicated a high risk of metastasis and recurrence." (PMID 31781310, 2019). "After demonstrating that CKS2 had aberrantly higher expression in RB samples compared to normal controls, we asked whether CKS2 contributed to cancer-associated phenotypes." (PMID 36096885, 2022). "Cancer Hallmarks Analytics Tool showed that CKS2 might be associated with proliferation, resisting cell death, angiogenesis, invasion, and metastasis." (PMID 31781310, 2019). "CKS2 has been implicated in promoting the aggressive behaviors of cancer cells." (PMID 31781310, 2019). "In addition to the causality demonstration, we inferred that the cancer-associated PI3K–AKT–mTOR pathway could potentially explain CKS2-mediated cancer phenotypes." (PMID 36096885, 2022). "To demonstrate that RNA-seq data could be valuable for causality studies of RB, we integrated transcriptomic analysis, gene functional enrichment, literature searching, experimental validation, and gene perturbation strategy to screen a novel cancer-causing gene CKS2 in RB." (PMID 36096885, 2022). "Importantly, reversed expression of CKS2 rescued cancer-associated phenotypes." (PMID 36096885, 2022). "This article reviews the biological function, mechanism of action and potential clinical significance of CKS2 in cancer, in order to provide a new theoretical basis for clinical molecular diagnosis, molecular targeted therapy and scientific research of cancer." (PMID 39188686, 2024). "CKS2 is an important protein in intracellular signal transduction and cell division, and the expression pattern of CKS2 has been studied in a variety of cancers." (PMID 39188686, 2024). "In this review, we summarize the role, mechanism and potential clinical significance of CKS2 in cancer pathology." (PMID 39188686, 2024). "Cyclin-dependent kinase subunit 2 (CKS2) is involved in cell cycle and proliferation processes, and based on these processes, CKS2 was identified as a cancer gene." (PMID 39188686, 2024). "Current studies on CKS2 and malignant tumors have some limitations, including lack of depth of study design, incomplete study subjects, and targeted CKS2 therapy for cancer." (PMID 39188686, 2024). "The current research on CKS2 in the field of malignant tumors is in the pre-clinical research stage such as cells or rodents, and the transformation of CKS2 inhibitors and combination therapy is also in the blank stage." (PMID 39188686, 2024). "Most existing preclinical trial reports suggest that CKS2 plays an important role in malignant tumors." (PMID 39188686, 2024).
cancer (continued). "Previous studies have indicated that high levels of cyclin-dependent kinase subunit 2 (CKS2) promote the progression of various cancers." (PMID 39548421, 2024). "Although specific inhibitors and combination therapy are beneficial to the treatment and prognosis of malignant tumors, there are relatively few studies on CKS2 at present." (PMID 39188686, 2024). "off-target effects and drug resistance should be limited in targeting CKS2 in cancer therapy, and delivery methods can be improved to address these challenges." (PMID 39188686, 2024). "Recently, CKS2 has been observed to exert oncogenic influence, showing high expression in various malignant tumors such as esophageal cancer, cervical cancer (CC), and non-small cell lung cancer (NSCLC)." (PMID 39548421, 2024). "Genomics studies have identified certain molecules that are important to the development of cancer, such as CKS2." (PMID 39188686, 2024). "At the same time, inhibition of CKS2 expression has also been found in CRC to inhibit cancer cell viability, reduce cyclin expression and lead to cell cycle arrest." (PMID 39188686, 2024). "Recent studies have shown that CKS2, as an oncogene, is significantly highly expressed in BC pathological tissues and cancer cells." (PMID 39188686, 2024). "Knockdown of CKS2 expression using CKS2-siRNA in cancer cells can significantly inhibit cell proliferation, cell migration and invasion." (PMID 39188686, 2024). "A large number of studies have shown that CKS2, as an oncogene, is highly expressed in digestive tract malignant tumors and is involved in the occurrence and development of various digestive system tumors." (PMID 39188686, 2024). "The transcription factor E2F1 enhances the expression of CKS2 by binding to its promoter, and CKS2 regulates the PI3K/AKT pathway associated with cancer." (PMID 38920989, 2024). "CKS2 has been identified as a potential prognostic marker and is overexpressed in a variety of cancers." (PMID 39188686, 2024). "Overexpression of CKS2 has been shown to promote cell proliferation in cell lines of multiple cancer types, while CKS2 knock-out induces cell cycle arrest and apoptosis, and inhibits cell growth, migration, and tumorigenesis in mice." (PMID 39188686, 2024). "In cell lines of multiple cancer types, overexpression of CKS2 has been shown to promote cell proliferation, metastasis, and migration and lead to poor prognosis." (PMID 39188686, 2024). "At a macro level, most of the current research designs on CKS2 in the field of malignant tumors are still at the stage of cell or rodent research, and corresponding clinical studies are lacking." (PMID 39188686, 2024). "CKS2 is closely related to the occurrence and development of a variety of diseases, including cancer, and previous studies have found that CKS2 acts as an oncogene and is abnormally expressed in a variety of human malignancies." (PMID 39188686, 2024). "Accumulating evidence suggests that CKS2 is an oncoprotein that promotes cancer tumorigenicity and progression, and that CKS2 levels in PTC correlate with the expression of its downstream genes, including cyclin B1 and CDK1." (PMID 39188686, 2024). "Overexpression of CKS2 is observed in many types of cancer and is thought to promote the proliferation and survival of cancer cells." (PMID 37240140, 2023). "Overexpression and upregulation of CKS2 have been reported in breast, gastric, colorectal, and hepatocellular cancer." (PMID 37373974, 2023). "In the previous study, DLX4 affected the progression of cancer by mediating the expression of YB-1 and CKS-2." (PMID 37744456, 2023). "Cyclin-dependent kinase regulatory subunit 2 (CKS2) is a potential prognostic marker and is overexpressed in various cancers." (PMID 35663965, 2022).
cancer (continued). "CKS2 can positively regulate cell proliferation, invasion, and migration to promote the progression of certain cancers." (PMID 35410253, 2022). "The mechanistic bridge between upregulated CKS2 and carcinogenesis of human cancers also involved DNA damage responses and DNA replication." (PMID 35693634, 2022). "E2F1 and CKS2 were both highly expressed in 21 cancer types and such positive correlation was also observed in our RB clinical data." (PMID 36096885, 2022). "More and more evidence suggests the oncogenic function of overexpressed CDC28 protein kinase regulatory subunit 2 (CKS2) in various human cancers." (PMID 35935749, 2022). "According to the qPCR screening, a cancer gene CKS2 was validated as the most induced cell cycle regulator when OTUD6A was overexpressed." (PMID 33669244, 2021). "To further evaluate CKS2 expression in human cancers, we examined pan-cancer RNA-seq data from TCGA database." (PMID 34729099, 2021). "In our research, CKS2 interacts with maternal embryonic leucine zipper kinase and Forkhead Box M1 (FOXM1), which are closely related with malignant tumors, indicating that CKS2 plays an important role in lung ACA." (PMID 33083148, 2020). "The aberrantly high expression of CKS2 observed in in different cancers including EC was correlated with patient’s poor prognosis." (PMID 32426838, 2020). "Overexpression of CKS1B and CKS2 is observed in multiple human cancers, including various MLL-rearranged (MLLr) AML subtypes." (PMID 28939057, 2018). "Overexpression of CKS2 in PDAC compared with normal tissues has also been reported in the Oncomine database, and data from the cbioportal database showed that CKS2 is amplified in many types of cancer." (PMID 29764514, 2018). "Overexpression of CKS1B and CKS2 has been documented in a variety of cancers, downstream of a variety of oncogenes, and their high expression has been correlated with poor prognosis." (PMID 28939057, 2018). "Cks1 and Cks2 have been shown to be overexpressed in many cancers and this phenotype correlates with poorer prognosis." (PMID 29383129, 2017). "CKS2 expression was significantly upregulated in CRC compared with the adjacent non-cancer and normal colorectal tissues." (PMID 24137409, 2013). "These limitations also make targeting CKS2 challenging in cancer therapy." (PMID 39188686, 2024). "Abnormal expression of CKS2 has been found to promote the aggressive behavior of cancer cells." (PMID 39188686, 2024). "In addition, in the targeting of CKS2 in cancer therapy, the current treatment of cancer targeting CKS2 mainly focuses on the non-coding RNA level." (PMID 39188686, 2024). "As an oncogene, CKS2 regulates the occurrence and development of various cancers." (PMID 39188686, 2024). "This discrepancy suggests that the function of CKS2 may exhibit variability across different cancer types, and autophagy could potentially influence ferroptosis in CC cells by modulating GSH metabolism." (PMID 39548421, 2024). "In addition, CKS2 expression patterns are closely related to cancer type, stage and other clinical variables." (PMID 39188686, 2024). "These researchs suggest that CKS2 plays an important role in the regulation of cell cycle and apoptosis of cancer cells, and inhibiting the expression of this gene may be beneficial to prevent the proliferation of cancer cells and promote apoptosis." (PMID 39188686, 2024). "CDKN3, CKS2 and MNAT1 consist of serine/threonine kinases crucial for regulating cell cycle transition and are significantly implicated in the pathogenesis of numerous cancers." (PMID 39689117, 2024). "CKS2 may promote cancer invasion and may be a useful biomarker for predicting disease outcomes and the need for early preventive treatment." (PMID 39188686, 2024). "CKS2 and TPT1 have both been implicated in cancer, including as potential therapeutic targets." (PMID 40809150, 2024).
cancer (continued). "In addition to miRNAs, long non-coding RNAs (lncRNAs) also appear to be involved in the regulation of pathological processes targeting CKS2 in cancer." (PMID 39188686, 2024). "In addition to regulating cell cycle and promoting cancer migration and invasion in human malignancies, CKS2 has also been found to be involved in the regulation of cancer angiogenesis and drug resistance." (PMID 39188686, 2024). "The unique biochemical characteristics of CKS2 make it a potential cancer biomarker." (PMID 39188686, 2024). "CKS2 is generally elevated in cancer, plays a role in almost all aspects of cancer biology (such as cell proliferation, invasion, metastasis, and drug resistance) through multiple mechanisms regulating certain important genes, and is associated with clinicopathological features of patients." (PMID 39188686, 2024). "CKS2 is a key regulator of the cell cycle and highly expressed in many cancers." (PMID 37719710, 2023). "Validation of G6PC and CKS2 expression and survival analysis in a variety of cancers." (PMID 35984176, 2022). "T-cell depletion and high expression of immune checkpoints predict a worse prognosis in patients, which may explain the cancer-promoting effect of CKS2 in tumors." (PMID 35663965, 2022). "Numerous reports have demonstrated that CKS2 expression is often elevated in various cancers, including lymphatic cancer, bladder cancer, breast cancer, cervical cancer, nasopharyngeal carcinoma, melanocytic carcinoma, esophageal squamous cell carcinoma, hepatocellular carcinoma, and Wilms tumor." (PMID 35663965, 2022). "CKS2 is known as a carcinogenesis factor in many cancers including EC." (PMID 32426838, 2020). "Moreover, CKS1B and CKS2 are frequently overexpressed in various cancers, including multiple myeloma and breast cancer, correlating with increased proliferation and poor prognosis." (PMID 28939057, 2018). "Therefore, we speculate that CKS2 may be a new candidate potential target for cancer therapy, and inhibition of CKS2 may be a promising cancer treatment approach." (PMID 39188686, 2024). "Therefore, CKS2 may be a potential biomarker for cancer diagnosis and prognosis, and may also be a target for cancer therapy." (PMID 39188686, 2024). "Besides, based on GENPIA, E2F1 and CKS2 had significantly positive co-expression in 21 of 33 types of cancer, which might be a possible reason why CKS2 always frequently elevated in many cancers." (PMID 36096885, 2022). "CCNB1, CKS2, MKI67, RRM2, TK1 and TOP2A were found with positive clinical correlation to GLEASON SCORE, and we could clearly identify the core factors as cancer risk factors, the expression level increased as Gleason score elevated." (PMID 32266115, 2020). "CKS2 can increase cyclin, cyclin A, cyclin B1 and CDK1, thereby promoting cancer cell proliferation." (PMID 39188686, 2024). "In addition, CKS2 may be a marker of cancer metastasis or poor prognosis." (PMID 39188686, 2024). "To characterize the potential functional role of CKS2, we analyzed genes whose expression parallels that of CKS2 based on RNA sequencing data from PDAC tissues in The Cancer Genome Atlas." (PMID 29764514, 2018). "CKS2 protein levels were higher in PDAC cell lines BxPC-3 and CFPAC-1 than in immortalized non-cancer pancreatic duct epithelial cell line HPDE6-C7." (PMID 29764514, 2018). "The present study identified that CKS2 was overexpressed at the mRNA and protein levels in CRC tissues in comparison with the adjacent non-cancer and normal colon tissues." (PMID 24137409, 2013). "There is accumulating evidence that CKS2 expression, similar to that of CKS1, is upregulated in a variety of malignant tumors, including those of the prostate, bladder and liver." (PMID 24137409, 2013).